MALAT1 (metastasis associated lung adenocarcinoma transcript 1)
Diseases named in the same sentence as MALAT1 in open-access papers (continued):
Sharing a sentence is not in itself a finding about the gene and the disease.
osteoporosis (28 papers, 2019 to 2025). A condition of reduced bone mass, with decreased cortical thickness and a decrease in the number and size of the trabeculae of cancellous bone (but normal chemical composition), resulting in increased fracture incidence. "Metastasis-associated lung adenocarcinoma transcript-1 (MALAT-1) protects against osteoporosis by inhibiting osteoclast differentiation via TEA domain family member 3 (Tead3)/NFATc1 signaling." (PMID 40873591, 2025). "Altogether, MALAT1 is an lncRNA implicated in osteogenic differentiation and potentially linked to the pathogenesis of osteoporosis." (PMID 39156986, 2024). "Collectively, these findings indicate that Malat1 deficiency promotes osteoporosis under both physiological and inflammatory conditions." (PMID 38493144, 2024). "Malat1 deficiency disrupts bone remodeling and results in osteoporosis through reduced osteoblastic bone formation and increased osteoclastic bone resorption." (PMID 39714456, 2024). "Recent research has also linked MALAT1 to bone growth and suggested its involvement in osteogenic differentiation, potentially contributing to the development of osteoporosis." (PMID 39156986, 2024). "In conclusion, the low expression of MALAT1 was closely associated with the development of osteoporosis." (PMID 36760811, 2022). "MALAT1 was downregulated in osteoporosis, and its downregulation was associated with the degradation of MC3T3-E1 cells." (PMID 36760811, 2022). "Notably, single-cell RNA-seq analysis demonstrates an association of reduced MALAT1 expression in the osteoclast lineage with osteoporosis and bone metastasis." (PMID 38493144, 2024). "Notably, single-cell transcriptome analysis of clinical bone samples reveals that reduced MALAT1 expression in pre-osteoclasts and osteoclasts is associated with osteoporosis and metastatic bone lesions." (PMID 38493144, 2024). "Notably, Malat1 deficiency in mice promotes osteoporosis and bone metastasis, which can be rescued by genetic add-back of Malat1." (PMID 36993303, 2023). "However, considering that reduced MALAT1 expression in pre-osteoclasts and osteoclasts is associated with osteoporosis and bone metastasis, our loss-of-function approach, coupled with re-expression of Malat1 in Malat1-deficient mice and cell lines, is suitable for this investigation." (PMID 38493144, 2024). "In conclusion, our study demonstrated that quercetin could rescue TNFα-impaired BMSCs osteogenesis in vitro and osteoporosis-induced bone loss in vivo, in a Malat1-dependent manner, suggesting that quercetin may serve as a therapeutic candidate for osteoporosis treatment." (PMID 36983039, 2023). "In addition, MALAT1 can regulate cell mineralization and is associated with osteoporosis." (PMID 36035997, 2022). "It has been demonstrated that the elevated MALAT1 levels in normal tissues confer protection against osteoporosis and bone metastasis." (PMID 39851553, 2025). "We found that both Malat1 KO and conditional KO mice in the osteoblast lineage exhibit significant osteoporosis." (PMID 38234849, 2024). "LncRNA MALAT1 can not only act as a sponge of miR‐34a‐5p in cancer cells, but also enhance osteoblasts' activities in osteoporosis mice by mediating the miR‐34c/SATB2 axis." (PMID 38984969, 2024). "To assess the clinical relevance of MALAT1 in osteoporosis and bone metastasis, we analyzed single-cell RNA-seq data from human bone tissues." (PMID 38493144, 2024). "For instance, the lncRNA ROR/miR-145-5p axis promotes osteoblast proliferation in osteoporosis, and silencing of lncRNA MALAT1 enhances erastin-induced ferroptosis in endometriosis via the miR-145-5p/MUC1 signaling pathway." (PMID 39308922, 2024). "MALAT1 promoted osteogenic differentiation and inhibited cell apoptosis through the miR‐485‐5p/WNT7B axis, which suggested that MALAT1 is a potential target to alleviate osteoporosis." (PMID 39043618, 2024).
osteoporosis (continued). "This study identified Malat1 as an osteoporosis-suppressing and bone metastasis-inhibiting lncRNA that is downregulated during RANKL-triggered osteoclastogenesis." (PMID 38493144, 2024). "Osteoporosis and bone metastases are two bone disorders that are correlated with MALAT1 dysregulation." (PMID 39156986, 2024). "In the present study, by using genetically engineered mouse models, we identify Malat1 as a negative regulator of osteoporosis and bone metastasis." (PMID 38493144, 2024). "Altogether, these findings identify Malat1 as a lncRNA that protects against osteoporosis and bone metastasis." (PMID 38493144, 2024). "Based on previous studies, several ubiquitous lncRNAs, including Malat1, H19, Hotair, MEG3 and Dancr, were previously reported to be associated with osteoporosis." (PMID 36983039, 2023). "In the clinical study, plasma level of MALAT1 is negatively correlated with the disease severity of postmenopausal osteoporosis, which suggested MALAT1 as a promising indicator of osteoporosis." (PMID 36983039, 2023). "Further investigation revealed that Malat1 was involved in the regulating mechanism of quercetin on BMSCs osteogenesis and the mouse osteoporosis process." (PMID 36983039, 2023). "Altogether, these findings identify Malat1 as a lncRNA that suppresses osteoporosis and bone metastasis." (PMID 36993303, 2023). "Malat1 was also identified as the universal modulator of quercetin’s treatment effect on osteoporosis." (PMID 36983039, 2023). "The lncRNA Malat1 was shown to be the key modulating factor in the regulating mechanism of quercetin on in vitro BMSCs osteogenesis and in vivo osteoporosis development." (PMID 36983039, 2023). "LncRNA metastasis-associated lung adenocarcinoma transcript 1 (MALAT1) was reported to be downregulated in osteoporosis, and BMSCs-derived exosomal MALAT1 promoted osteoblast activity in osteoporotic mice." (PMID 37156809, 2023). "An analysis of the ceRNA network has unveiled that NEAT1/MALAT1-hsa-miR-32-3p-SP1/FZD6 and NEAT1/MALAT1-hsa-miR-22-3p-PTEN/ESR1/ERBB3/CSF1R/CDK6 are likely pivotal contributors to the pathogenesis of osteoporosis." (PMID 37814309, 2023). "This study aimed to investigate the effects of MALAT1 on osteogenic differentiation and cell apoptosis in osteoporosis." (PMID 36760811, 2022). "To further verify the potential roles of MALAT1 in osteoporosis, we further determined the effects of MALAT1 on the cellular function of MC3T3-E1 cells." (PMID 36760811, 2022). "LncRNA MALAT1 shuttled by BMSC-derived exosomes inhibits osteoporosis and lncRNA AFAP1-AS1 contained in exosome enhances resistance to trastuzumab." (PMID 35470736, 2022). "In conclusion, MALAT1 promoted osteogenic differentiation and inhibited cell apoptosis through the miR-485-5p/WNT7B axis, which suggested that MALAT1 is a potential target to alleviate osteoporosis." (PMID 36760811, 2022). "To further verify the roles of MALAT1 in osteoporosis, we determined its expression in MG-treated MC3T3-E1 cells." (PMID 36760811, 2022). "For instance, mesenchymal stem cell-derived MALAT1 promotes human osteogenic differentiation and suppresses the development of osteoporosis." (PMID 36760811, 2022). "The exosomes secreted by BMSCs contain lncRNA metastasis-associated lung adenocarcinoma transcript 1 (MALAT1), which can act as a sponge for miR-34c, increase the expression of SATB2 and help alleviate osteoporosis." (PMID 35505438, 2022). "To further clarify the roles of MALAT1 in osteoporosis, we detected the effects of MALAT1 overexpression on osteoporosis in vivo." (PMID 36760811, 2022). "Our results highlighted the potential of exosomal MALAT1 to prevent osteoporosis in OVX mouse models." (PMID 31659145, 2019). "Studies showed that MALAT1 delivered by bone marrow-derived MSC-secreted exosomes could alleviates osteoporosis, and knockdown of lncRNA BCAR4 was reported to alleviate osteoporosis." (PMID 37516879, 2023).
osteoporosis (continued). "The key mediating role of Malat1 in quercetin’s effect on osteoporosis has also been covered." (PMID 36983039, 2023). "Moreover, MALAT1 promotes osteoporosis progression through inhibiting osteogenic differentiation of bone marrow mesenchymal stem cells." (PMID 36760811, 2022). "Metastasis-associated lung adenocarcinoma transcript 1 (MALAT1) located at human chromosome 11q13 and mouse chromosome 19q with a length of 8.5 kb is a well-studied lncRNA in human diseases including osteoporosis." (PMID 36760811, 2022). "A previous report has revealed that MALAT1 enhances osteoblast activity to alleviate osteoporosis." (PMID 36760811, 2022). "However, emerging evidence reveals that MALAT1 protects against osteonecrosis of the femoral head and osteoporosis." (PMID 36760811, 2022). "MALAT1 was downregulated in osteoporosis models in vivo and in vitro." (PMID 36760811, 2022). "One study reported that MSCs-derived exosomal MALAT1 could be transferred to osteoblasts and alleviate the symptoms of osteoporosis." (PMID 36333764, 2022). "The coupling mechanism between MALAT1 and miR-124 could be a remarkable and efficient direction for future osteoporosis therapy." (PMID 32791451, 2020). "In summary, our study provides evidence that BMSCs-derived exosomal MALAT1 may contribute to enhanced osteogenic activity and alleviated symptoms of osteoporosis in the mouse model by acting as a miR-34c sponge to upregulate SATB2 expression." (PMID 31659145, 2019). "Furthermore, research indicates that the expression of LncRNA MALAT1 is decreased during the process of osteoclast differentiation, leading to bone resorption, ultimately contributing to low bone mineral density and the development of osteoporosis." (PMID 38984969, 2024). "Furthermore, we detected that the upregulation of MALAT1 could attenuate the symptoms of osteoporosis in mice." (PMID 31659145, 2019). "In a mouse model of osteoporosis, BM‐MSC‐EVs that contain MALAT1 enhance osteoblast activity by regulating the miR‐34c/SATB2 axis, thereby alleviating osteoporosis." (PMID 40290901, 2025). "It is hypothesized that LncRNA MALAT1 plays a significant role in bone repair by promoting osteoblast function and inhibiting osteoclast activity, thereby serving as a potential therapeutic target for the prevention and treatment of osteoporosis and bone defects." (PMID 38984969, 2024). "Several lncRNAs, including Malat1, H19, HOTAIR, MEG3 and DANCR, were largely involved in the osteoporosis." (PMID 36983039, 2023). "In this study, MALAT1 sponged miR-485-5p to activate WNT7B, which was downregulated in osteoporosis model in vivo and in vitro." (PMID 36760811, 2022). "In this study, dysregulated MALAT1 contributed to the degradation of MC3T3-E1 cells and the development of osteoporosis via sponging miR-485-5p." (PMID 36760811, 2022). "It was shown that MALAT1 and TUG1 can serve as vital therapeutic targets, especially for osteoporosis patients." (PMID 32791451, 2020). "Taken together, our results suggest that Malat1 inhibits osteoclast differentiation and protects against osteoporosis and bone metastasis without affecting osteoblastic bone formation." (PMID 38493144, 2024). "Before injecting tumor cells, we conducted μCT scanning and confirmed that at this age, only female Malat1−/− mice, but not female Malat1+/+ and Malat1−/−;Malat1Tg/Tg mice, exhibited signs of osteoporosis." (PMID 38493144, 2024). "Furthermore, Li demonstrated that MALAT1 facilitated BMSC osteogenic differentiation and repressed macrophages osteoclastic differentiation during osteoporosis through miR-124-3p/IGF2BP1/Wnt/β-catenin axis." (PMID 37156809, 2023). "Inhibiting the expression of MALAT1 can reduce ALP activity and inhibit osteogenic differentiation of bone marrow mesenchymal stem cells (BMSCs) by enhancing the activation of the MAPK signaling pathway that promotes the progression of osteoporosis." (PMID 36035997, 2022).
osteoporosis (continued). "Taken together, the results suggest that oe-MALAT1, oe-SATB2 or si-miRNA-34c could help prevent osteoporosis in OVX mice." (PMID 31659145, 2019). "However, functional evidence of MALAT1 alterations having a role in low BMD and osteoporosis is lacking." (PMID 38493144, 2024).
Parkinson disease (28 papers, 2017 to 2025). A progressive degenerative disorder of the central nervous system characterized by loss of dopamine producing neurons in the substantia nigra and the presence of Lewy bodies in the substantia nigra and locus coeruleus. "Metastatic-associated lung adenocarcinoma transcript 1 (MALAT1), also known as the nuclear-enriched abundant transcript 2, is a lncRNA that is a crucial factor in the pathogenesis of Parkinson’s disease (PD)." (PMID 37744008, 2023). "In Parkinson’s disease (PD) mice, the lncRNA metastasis-associated lung adenocarcinoma transcript 1 (MALAT1) was highly expressed and promoted neuroinflammation through inducing inflammasome activation and reactive oxygen species (ROS) production." (PMID 36827545, 2023). "GAS5 and MALAT1 have a close association with Parkinson’s disease and aging and are involved in neurodegeneration." (PMID 36710930, 2022). "The role of MALAT1 was studied in a mouse model of Parkinson disease where it was associated with apoptosis of dopaminergic neurons of the disease." (PMID 30514825, 2019). "Furthermore, two SNPs, rs3200401 (C>T) and rs4102217 (G>C), were identified in MALAT1 in PD patients that increased the risk of developing Parkinson’s three-fold." (PMID 39768369, 2024). "In support, others have shown that the recruitment of Dnmts by MALAT1 hypermethylated the DNA of suppressor of cytokine signaling 3 in the Parkinson’s disease model and CASP3 in the autism model." (PMID 40650203, 2025). "It has been reported that Malat1 suppresses Nrf2 through epigenetic mechanisms, leading to increased inflammasome activation and elevated ROS generation in both Parkinson's disease mouse models and microglial cells." (PMID 41208834, 2025). "Intriguingly, MALAT1 can promote neuroinflammation by NRF2 inhibition in a Parkinson’s Disease (PD) mouse model." (PMID 36361952, 2022). "Both CSF and plasma levels of the lncRNA MALAT1 are downregulated in AD patients compared to control and Parkinson’s disease (PD) individuals." (PMID 35052379, 2021). "For instance, MALAT1 is able to sponge miR-124 and thus facilitates cell apoptosis in Parkinson’s disease." (PMID 32315984, 2020). "For example, MALAT1 dysregulation has already been described in Parkinson’s disease." (PMID 36947499, 2023). "Also, resveratrol improves Parkinson’s disease-like phenotype by suppressing neuronal apoptosis by modulating the MALAT1/miR-129/SNCA signaling pathway." (PMID 33192306, 2020). "Furthermore, MALAT1, ranked second in Parkinson disease (PD), has been reported to show decreased expression in PD and to inhibit α-synuclein protein expression, thereby providing a neuroprotective effect in PD65." (PMID 28051121, 2017). "Furthermore, the expression profiles of the lncRNAs Malat1, Neat1, and Gas5 were significantly dysregulated in the Parkinson's disease model, with Malat1 and Neat1 showing notable upregulation, which has been associated with enhanced oxidative stress and neuroinflammation." (PMID 41208834, 2025). "The long non-coding RNA MALAT1 suppresses NRF2 expression through epigenetic mechanisms, promoting inflammasome activation and ROS production in Parkinson’s disease (PD) mouse and microglial cell models, thereby exacerbating neuroinflammation." (PMID 40258841, 2025). "LPS/ATP-induced MALAT1 upregulation leads to the increased ROS levels and inflammasome activation by regulating EZH2-mediated epigenetic repression in Parkinson's disease (PD)." (PMID 34899921, 2021). "Therefore, it is predicted that LncRNA MALAT1 and lncRNA HOTAIR interact synergistically to downregulate the miR-205-5p and influence the neuroinflammation in parkinsonism." (PMID 34066949, 2021). "Moreover, plasma MALAT1, miR-125b, FOXQ1, PTGS2, and CDK5 could distinguish AD patients from controls, while only plasma MALAT1, miR-125b, and PTGS2 could discriminate AD patients from Parkinson’s disease patients." (PMID 36947499, 2023).
esophageal cancer (27 papers, 2016 to 2025). A primary or metastatic malignant neoplasm involving the esophagus. "Simultaneously, m6A-deficient MALAT1 rescued the metastatic nature of esophageal cancer cells, suggesting the functional role of m6A marks on MALAT1." (PMID 34065036, 2021). "For example, MALAT1 was found to regulate esophageal cancer growth by modifying the ATM-CHK2 pathway in esophageal cancer." (PMID 38877481, 2024). "The knockdown of MALAT1 in esophageal cancer can inhibit the migration and invasion ability of esophageal cancer cells." (PMID 38877481, 2024). "Mechanistic studies on MALAT1 have been performed in the context of lung, breast, cervix, and esophageal cancers, where MALAT1 expression is often dysregulated." (PMID 37325561, 2023). "Taken together, these results suggested that TRA2A can directly bind with MALAT1, and regulate the lncRNA expression in esophageal cancer cells." (PMID 34234858, 2021). "The results illustrated that the RNA level of MALAT1 in ESCA (esophageal cancer), LAML (acute myeloid leukemia), and STAD (stomach adenocarcinoma) was higher than normal tissues." (PMID 34308750, 2021). "Together, these findings elucidated that TRA2A triggers carcinogenesis via MALAT1 mediated EZH2/β-catenin axis in esophageal cancer cells." (PMID 34234858, 2021). "Metastasis-associated lung adenocarcinoma transcript 1 (MALAT1) were down-regulated, while PlncRNA-1, TUG1 and Linc-POU3F3 were up-regulated in esophageal cancer." (PMID 28388588, 2017). "Lastly, over-expressed Ezh2 combined with MALAT1 down-regulation completely reversed the si-MALAT1-mediated repression of β-catenin and Lin28 in esophageal cancer cells." (PMID 27015363, 2016). "Down-regulation of MALAT1 decreased the expression of β-catenin, Lin28 and Ezh2 genes, while over-expressed Ezh2 combined with MALAT1 down-regulation completely reversed the si-MALAT1-mediated repression of β-catenin and Lin28 in esophageal cancer cells." (PMID 27015363, 2016). "Given that MALAT1 modulated Ezh2 expression in esophageal cancer cells, then we examined the expression of Ezh2 in 40 ESCC tissues." (PMID 27015363, 2016). "Silencing of MALAT1 expression inhibited cell proliferation, migration and tumor sphere formation, while increasing cell apoptosis of esophageal cancer in vitro." (PMID 27015363, 2016). "Tumor cell proliferation in esophageal cancer is suppressed by Malat1 silencing." (PMID 35309141, 2022). "Thus we postulated that TRA2A regulates and activates the EZH2/β-catenin pathway by binding to MALAT1 and elevating its expression, hence promotes esophageal cancer progression." (PMID 34234858, 2021). "MALAT1 could enhance cell proliferation, G2/M cell cycle arrest, cell migration and invasion of esophageal cancer cells by up-regulating p21 and p27 expression and down-regulating B-MYB expression." (PMID 28388588, 2017). "To further explore the relationship between TRA2A and MALAT1, we analyzed the RNA expression correlation between TRA2A and MALAT1 in 184 esophageal cancer samples from TCGA." (PMID 34234858, 2021). "Functional studies also confirmed that the interaction between MALAT1 and TRA2A plays an important role in esophageal cancer cells." (PMID 34234858, 2021). "For instance, MALAT1-m6A modifications generated by the METTL3-METTL14 complex are important to the metastatic ability of esophageal cancer cells (ESCCs), but silencing METTL3 cannot recapitulate the phenotypes of impaired migration observed in MALAT1-Δm6A cells." (PMID 34315512, 2021). "miR-101, miR-217 and MALAT1 siRNA have common downstream genes like MIA2, HNF4G, ROBO1, CCT4 and CTHRC1, and miR-101 or miR-217 and MALAT1 were negatively correlated in 42 pairs of esophageal cancer tissue samples and adjacent normal tissues." (PMID 28388588, 2017).